CYP4F3 (cytochrome P450 family 4 subfamily F member 3)
Description:
A cytochrome P450 monooxygenase involved in the metabolism of various endogenous substrates, including fatty acids and their oxygenated derivatives (oxylipins). Mechanistically, uses molecular oxygen inserting one oxygen atom into a substrate, and reducing the second into a water molecule, with two electrons provided by NADPH via cytochrome P450 reductase (CPR; NADPH-ferrihemoprotein reductase). May play a role in inactivation of pro-inflammatory and anti-inflammatory oxylipins during the resolution of inflammation. [Isoform CYP4F3A]: Catalyzes predominantly the oxidation of the terminal carbon (omega-oxidation) of oxylipins in myeloid cells, displaying higher affinity for arachidonate metabolite leukotriene B4 (LTB4). Inactivates LTB4 via three successive oxidative transformations to 20-hydroxy-LTB4, then to 20-oxo-LTB4 and to 20-carboxy-LTB4. Has omega-hydroxylase activity toward long-chain fatty acid epoxides with preference for 8,9-epoxy- (5Z,11Z,14Z)-eicosatrienoate (EET) and 9,10-epoxyoctadecanoate. Omega-hydroxylates monohydroxy polyunsaturated fatty acids (PUFAs), including hydroxyeicosatetraenoates (HETEs) and hydroxyeicosapentaenoates (HEPEs), to dihydroxy compounds. Contributes to the degradation of saturated very long-chain fatty acids (VLCFAs) such as docosanoic acid, by catalyzing successive omega-oxidations to the corresponding dicarboxylic acid, thereby initiating chain shortening. Has low hydroxylase activity toward PUFAs. [Isoform CYP4F3B]: Catalyzes predominantly the oxidation of the terminal carbon (omega-oxidation) of polyunsaturated fatty acids (PUFAs). Participates in the conversion of arachidonic acid to 20-hydroxyeicosatetraenoic acid (20-HETE), a signaling molecule acting both as vasoconstrictive and natriuretic with overall effect on arterial blood pressure. Has high omega-hydroxylase activity toward other PUFAs, including eicosatrienoic acid (ETA), eicosapentaenoic acid (EPA) and docosahexaenoic acid (DHA). Can also catalyze the oxidation of the penultimate carbon (omega-1 oxidation) of PUFAs with lower efficiency. Contributes to the degradation of saturated very long-chain fatty acids (VLCFAs) such as docosanoic acid and hexacosanoic acid, by catalyzing successive omega-oxidations to the corresponding dicarboxylic acids, thereby initiating chain shortening. Omega-hydroxylates long-chain 3-hydroxy fatty acids, likely initiating the oxidative conversion to the corresponding 3-hydroxydicarboxylic fatty acids. Has omega-hydroxylase activity toward long-chain fatty acid epoxides with preference for 8,9-epoxy- (5Z,11Z,14Z)-eicosatrienoate (EET) and 9,10-epoxyoctadecanoate.
Synonyms: LTB4H; CYP4F; CPF3; CYPIVF3
Tractability: Small molecule: it belongs to a druggable protein family. Antibody: UniProt predicts a signal peptide or a membrane-spanning region. PROTAC: ubiquitination databases record sites on it; its protein half-life has been measured; a small molecule that binds it is known.
Target class: Enzyme; Oxidoreductase
Gene: Protein-coding gene on chromosome 19 (15,640,795 to 15,662,825, forward strand). Ensembl gene ENSG00000186529.
Subcellular location: Endoplasmic reticulum membrane; Microsome membrane
Pathways (Reactome):
Metabolism: Eicosanoids; Fatty acids; Miscellaneous substrates; Synthesis of Leukotrienes (LT) and Eoxins (EX)
Gene Ontology:
Molecular function: 20-aldehyde-leukotriene B4 20-monooxygenase activity; 20-hydroxy-leukotriene B4 omega oxidase activity; arachidonate omega-hydroxylase activity; leukotriene-B4 20-monooxygenase activity; oxidoreductase activity, acting on paired donors, with incorporation or reduction of molecular oxygen, reduced flavin or flavoprotein as one donor, and incorporation of one atom of oxygen; monooxygenase activity; 5(S)-hydroxyeicosatetraenoic acid dehydrogenase activity; fatty acid omega-hydroxylase activity; heme binding; iron ion binding; long-chain fatty acid omega-hydroxylase activity; oxidoreductase activity, acting on paired donors, with incorporation or reduction of molecular oxygen; very long-chain fatty acid omega-hydroxylase activity
Biological process: arachidonate metabolic process; icosanoid metabolic process; leukotriene metabolic process; menaquinone catabolic process; phylloquinone catabolic process; leukotriene B4 catabolic process
Cellular component: endoplasmic reticulum membrane
Genetic constraint (gnomAD): Loss-of-function variants: 52 observed, 57.76 expected, observed/expected ratio (o/e) 0.9, 90% interval 0.72 to 1.13. The upper end of that interval is the gene's LOEUF score, 1.13, which puts it in group 4 of 6, group 1 being the genes least tolerant of losing a copy. Missense variants: 715 observed, 699.02 expected, observed/expected ratio (o/e) 1.02, 90% interval 0.96 to 1.09. Synonymous variants: 244 observed, 271.78 expected, observed/expected ratio (o/e) 0.9, 90% interval 0.81 to 1.
Homologues: Orthologues: chimpanzee CYP4F3 (99% identical), pig CYP4F3 (85% identical), rat Cyp4f18 (82% identical), mouse Cyp4f18 (81% identical), tropical clawed frog cyp4b1.5 (43% identical), tropical clawed frog cyp4b1.2 (42% identical), tropical clawed frog XB5810926 (42% identical), zebrafish cyp4t8 (38% identical), Drosophila melanogaster Cyp4c3 (33% identical), zebrafish cyp4f3 (33% identical), Drosophila melanogaster Cyp4d2 (32% identical), Drosophila melanogaster Cyp312a1 (32% identical), and 25 more. Paralogues in human: CYP4F2 (88% identical), CYP4F11 (83% identical), CYP4F12 (78% identical), CYP4F8 (77% identical), CYP4F22 (65% identical), CYP4A11 (45% identical), CYP4A22 (44% identical), CYP4B1 (43% identical), CYP4X1 (40% identical), CYP4Z1 (37% identical), CYP4V2 (33% identical), CYP19A1 (22% identical).